IL1B (interleukin 1 beta)
Diseases named in the same sentence as IL1B in open-access papers (continued):
Sharing a sentence is not in itself a finding about the gene and the disease.
periodontitis (continued). "Higher salivary concentration of IL-1β from patients with periodontitis has been detected in several earlier studies, 49,50." (PMID 23637817, 2013). "Our main finding is that PTPα plays a central role in the connective tissue destruction of ligature-induced periodontitis possibly through the maintenance of focal adhesion dynamics in fibroblasts that enable IL-1β signaling and MMP-3 expression." (PMID 23940616, 2013). "It is frequently associated with subgingival biofilms of both chronic and aggressive periodontitis, and the diseased sites of the periodontium exhibit increased levels of the proinflammatory mediator interleukin (IL)-1β." (PMID 23936223, 2013). "A review and meta-analysis showed that IL-1α and IL-1β genetic variations are significant contributors to chronic periodontitis in Caucasians." (PMID 23691333, 2013). "In the present study, the effects of FMD and Q-SRP on IL-17 and IL-1β serum levels were evaluated and compared in patients with moderate-to-severe chronic periodontitis." (PMID 25512752, 2013). "A recent meta-analysis demonstrated that IL-1A and IL-1B genetic variations are significant contributors to chronic periodontitis." (PMID 24151615, 2013). "Dysregulation of IL-1β activity can result in chronic diseases such as periodontitis (reviewed in 24,26)." (PMID 23936223, 2013). "In the natural healing process of periodontitis, the expression of IL-1β and TNF-α reduced markedly." (PMID 23326020, 2012). "Studies also have shown that when periodontitis exists, some inflammatory cytokines, such as IL-1β and TNF-α, are significantly increased in periodontal tissue, gingival crevicular fluid, or peripheral blood." (PMID 23326020, 2012). "In periodontitis patients, IL-1β production increased via circulating monocytes or oral polymorphonuclear neutrophils (PMNs)." (PMID 22315682, 2012). "The periodontitis healing condition was assessed, and the expression of interleukin-1β (IL-1β), tumor necrosis factor-α (TNF-α), and bFGF were tested by immunohistochemistry." (PMID 23326020, 2012). "In the gingival crevicular fluid, elevated IL-6, TNF-α, and IL-1β were reported in persons afflicted with periodontitis." (PMID 22315682, 2012). "The surface of inflammatory infiltrate, alveolar bone loss, attachment loss, and expression of IL-1β and TNF-α in the stress group were higher than those in the periodontitis group at weeks 2 and 4 (P < 0.05)." (PMID 23326020, 2012). "Because IL-1β is produced in the active phase of periodontitis, and A. actinomycetemcomitans is coupled with aggressive forms of this biofilm disease, we selected A. actinomycetemcomitans as a model organism to study the IL-1β – bacterium interaction." (PMID 21533109, 2011). "Statins also reduce the production of IL-1β and TNFα, inflammatory cytokines which are known to play a pivotal role in periodontitis." (PMID 22203908, 2011). "In chronic biofilm infection, periodontitis, Aggregatibacter actinomycetemcomitans requires tight adherence (tad)-locus to form biofilms, and tissue destroying active lesions contain more IL-1β than inactive ones." (PMID 21533109, 2011). "Periodontitis group showed a significant increase in periodontal IL-1β, LPO, 8-OHdG, apical migration of JE, alveolar bone resorption and number of PMNs." (PMID 22615625, 2010). "In combination with IL1A -889 and IL1B +3954, the IL1RN R-allele was reported to have a relationship with periodontitis susceptibility." (PMID 20339487, 2010). "Serum IL-1β in patients with untreated aggressive periodontitis showed a positive correlation with smoking." (PMID 20170537, 2010). "CRP, IL-1β, IL-6, and TNF-α have been associated with the presence of various bacterial infections, including periodontitis." (PMID 20407653, 2009). "Additionally, the study's findings showed that gingival tissue in a periodontitis model had higher levels of IL1-β and TNF-α than the control group (p ≤ 0.01)." (PMID 41625272, 2026).
periodontitis (continued). "In a rat model of periodontitis, EGCG reduced bone loss by downregulating NLRP3 and NF-κB expression in periodontal tissues, whereas curcumin improved PDL integrity by upregulating the anti-inflammatory cytokine IL-10 and suppressing IL-1β and IL-6 expression." (PMID 41596738, 2026). "In the paper that compared cytokine levels for 54 periodontitis patients and 40 healthy controls, cytokines IL‐1β, IL‐4, IL‐6, IL‐10, IL‐17A, IL‐17F, IL‐21, IL‐22, IL‐23, IL‐25, IL‐31, IL‐33, IFN‐γ, sCD40L and TNF‐α were measured in saliva and serum at baseline, 3, 6 and 12 months after treatment." (PMID 41580300, 2026). "Furthermore, in a periodontitis mouse model, OMVs were found to facilitate signal transduction via the NF-κB pathway, leading to the activation of inflammasomes and the release of IL-1β and IL-1897." (PMID 41583519, 2026). "Chronic infections, including periodontitis, might increase circulating cytokines and factors, such as C-reactive protein, interleukin-1 beta, interleukin-6, tumor necrosis factor-alpha, and prostaglandin-E2." (PMID 39229981, 2025). "The proposed explanation for this association is based on the idea that periodontitis could influence inflammatory biomarkers, such as TNF-α, Interleukin 1 Beta (IL-1β), and Interleukin 6 (IL-6), which may contribute to increased blood pressure." (PMID 40002786, 2025). "This study aimed to evaluate the association between periodontitis stage and grade with systemic levels of C-reactive protein (CRP), interleukin-1β (IL-1β), interleukin-6 (IL-6), and tumor necrosis factor-alpha (TNF-α) and assess changes following standardized non-surgical periodontal therapy." (PMID 41440349, 2025). "Local inflammatory responses in periodontitis are characterized by the release of cytokines (IL-1β, IL-6, TNF- α), prostaglandins, and matrix metalloproteinases (MMPs) from resident and infiltrating immune cells, leading to tissue destruction and alveolar bone resorption." (PMID 40941475, 2025). "Additionally, IL-1β is a proinflammatory cytokine that promotes alveolar bone resorption in periodontitis through the induction of cellular proteinases." (PMID 40692535, 2025). "On the other hand, in NLRP3-KO macrophages, the absence of the feedback loop reduces ROS levels and, although they maintain the ability to induce mtDNA release and activate AIM2, IL-1β secretion and pyroptosis are significantly decreased in both periodontitis and peri-implantitis scenarios." (PMID 40490723, 2025). "Notably, preclinical research has identified CCL2 as a key chemokine that is significantly upregulated in periodontitis, promoting inflammation and upregulating pro-inflammatory cytokines such as TNFα and IL1β." (PMID 40565042, 2025). "Among them, cytokines such as TNF-α, IL-1β, and IL-6 are highly expressed in patients with periodontitis and promote bone resorption by directly or indirectly supporting not only inflammation but also soft tissue degradation, lymphocyte promotion, and osteoclast formation." (PMID 40733170, 2025). "Among T1DM patients, IL-1β may help differentiate between gingivitis and periodontitis, while IL-8 appears to play a broader role in disease activity." (PMID 41280935, 2025). "In this study, we found that periodontitis and periodontitis-associated metabolite Ile enhanced NF-κB signaling in IECs to impair epithelial barrier function and increase the expression of pro-inflammatory cytokines (TNF-α, IL-6, and IL-1β)." (PMID 41394102, 2025). "Additionally, salivary levels of NLRP3, ASC, and IL-1β were higher in chronic or aggressive periodontitis patients than in healthy patients; however, levels of caspase-1 were not altered." (PMID 41440367, 2025). "As a result of the study, GLE down-regulated the expression levels of pro-inflammatory mediator proteins increased by PG-LPS in a concentration-dependent manner, and increased gene levels of il-6, il-1β, and tnf-α, the major pro-inflammatory cytokines in periodontitis." (PMID 40733170, 2025).
periodontitis (continued). "To verify whether the observed synergistic activation of the COX-2-PGE2 axis is specific for TNF, we analyzed the effect of several cytokines that are involved in periodontitis pathogenesis, including IL-1β, IL-1α, and interferon-α (IFNα)." (PMID 40178270, 2025). "The significant correlation between cortisol and IL-6 and IL-1β also suggests that specific inflammatory pathways may mediate the stress–periodontitis axis." (PMID 40843742, 2025). "ECE also reduced tooth mobility, prevented alveolar bone loss, decreased inflammatory cell infiltration, IL-1β production, and MMP-2/-9 expression in gingival tissues of periodontitis rats model demonstrating that ECE has important therapeutic effects for the alleviation of periodontal disease." (PMID 40736688, 2025). "A comparison of pro-inflammatory markers (NLRP3 and IL-1β in serum and saliva) with the presence and parameters of periodontitis showed significant differences in NLRP3 levels in both saliva (p = 0.038) and serum (p = 0.021), with higher levels in patients with periodontitis." (PMID 40572711, 2025). "Neither IL-1β nor IL-6 demonstrated significant independent associations with Grade C periodontitis in the multivariate analysis." (PMID 40843742, 2025). "Additionally, these antibodies significantly reduced the transcript levels of the pro-inflammatory cytokines IL-1β and IL-6, which are markers of periodontitis." (PMID 39699191, 2025). "Similarly, in periodontitis, IL1B plays a crucial role, and it considered one of the primary inflammatory mediators in the disease’s pathogenesis." (PMID 40002889, 2025). "Moreover, IL-1β is a pivotal mediator in the pathogenesis of periodontitis, with studies indicating its role in exacerbating periodontal inflammation and its reduction following periodontal therapy." (PMID 40863063, 2025). "We hypothesize that patients with more severe forms of periodontitis would exhibit higher salivary cortisol, as well as elevated levels of IL-1β and IL-6, reflecting a coordinated neuroendocrine inflammatory response associated with disease progression." (PMID 40843742, 2025). "In a rat periodontitis model, cashew gum polysaccharide (CG‐P)‐containing oral gel significantly reduced alveolar bone loss, decreased the mRNA expression of TNF‐α, IL‐1β, RANKL, and the RANKL/OPG ratio, and lowered myeloperoxidase activity in gingival tissues." (PMID 41476843, 2025). "Notably, our data demonstrate LFS neutralizes the strong pro‐osteoclastogenic effect of IL‐1β—a key inflammatory cytokine in periodontitis." (PMID 41368333, 2025). "Similarly, low birth weight labor is linked to periodontitis through intermediary pro-inflammatory cytokines and chemokines, namely TNF-α, IL-1β, CRP, IL-1, IL-6 and IL-18." (PMID 41394354, 2025). "Following the 24 months of treatment with the regimen, the regimen was found to directionally reduce bacterial amount and diversity while also statistically significantly reducing critical biomarkers (IL-1β, MMP-1, MMP-9) associated with inflammation and periodontitis." (PMID 41303313, 2025). "Additionally, critical inflammatory mediators associated with periodontitis, such as iNOS, NLRP3, TNF‐α, and IL‐1β, were significantly modulated." (PMID 41020683, 2025). "Other studies indicate that calculus particles may promote bone resorption via IL-1β induction in patients with periodontitis." (PMID 40559160, 2025). "Periodontitis, characterized by chronic bacterial infection and subsequent host inflammatory response, triggers the release of pro-inflammatory cytokines including interleukin-1β (IL-1β), interleukin-6, and tumor necrosis factor-α (TNF-α)." (PMID 41153725, 2025). "Researchers further conducted in vivo experiments with periodontitis mouse models and reported that F. nucleatum OMV-treated periodontitis model mice presented greater numbers of osteoclasts, more widespread alveolar bone damage, and significant increases in the levels of IL-1β, IL-6, and TNF-α." (PMID 41208888, 2025).
periodontitis (continued). "During periodontitis, IL-6 and IL-1β have an opposite role in connective tissue turnover." (PMID 40182222, 2025). "Indeed, salivary IL-1β proved to be a useful biomarker for identifying periodontitis and monitoring improvement after treatment, especially in non-smoking patients." (PMID 41440367, 2025). "In vivo, the exclusive reliance on a rat periodontitis model lacks representativeness, and the restricted focus on two inflammation-associated cytokines (TNF-α and IL-1β) overlooks other critical mediators (e.g. IL-6) and bone formation markers (e.g. BMP-2, OCN)." (PMID 40958806, 2025). "Spearman's correlation analysis was conducted to examine the relationships between variables.In saliva samples, NLRP3, caspase-1, IL-1β, and IL-18 were the highest in the periodontitis group (p < 0.005), while IL-37 was highest in the healthy group (p < 0.005)." (PMID 40267956, 2025). "Likewise, in periodontitis patients, IL-1β triggers cell chemotaxis, collagen destruction via upregulating the secretion of matrix metalloproteinases (MMPs), and bone resorption by increasing osteoclastogenesis." (PMID 40136507, 2025). "Our data were consistent with a previous report where the activated Piezo1 contrarily triggered M1 macrophage polarization in response to LPS, triggered overproduction of proinflammatory cytokines (e.g. TNF-α and IL-1β) and ultimately contributed to collagen degradation in periodontitis." (PMID 38303078, 2024). "Periodontitis induces a chronic inflammatory response in the periodontal tissues, characterized by the release of pro-inflammatory cytokines such as interleukin-1 beta (IL-1β), TNF-α, and IL-6." (PMID 39189252, 2024). "Comparing the Average global expression profile of neutrophils from healthy PDL versus neutrophils from PDL with periodontitis revealed increased expression of genes such as Il1b, Il1rn, Cebpb, Colec12, Ptgs2, Zfp36, Egr1, Atf3, Csf1, and Lars2 in periodontitis." (PMID 39588378, 2024). "Nevertheless, systematic reviews and meta-analyses have identified significant associations between genetic variants in genes like interleukin 1A (IL-1A), interleukin 1B (IL-1B), IL6, IL10, the matrix metalloprotease 3 (MMP-3), and matrix metalloprotease 9 (MMP-9) and periodontitis risk." (PMID 39337647, 2024). "Recent studies have shown that NLRP3 and caspase‐4 inflammasomes in human periodontal ligament stem cells (PDLSCs) and gingival fibroblasts (GFs) can be activated under an inflammatory environment, resulting in pyroptosis and IL‐1β secretion, exacerbating periodontitis." (PMID 37710420, 2024). "As periodontitis is both a local and a systemic condition, we determined the effect of Pg-inoculation on the induction of systemic inflammation by assessing the levels of proinflammatory cytokines such as IL-1β, TNF-α, IL-6, GM-CSF, VEGF, IL-17, and KC." (PMID 38892314, 2024). "Finally, we compared the expression levels of periodontitis-related genes, such as Il1b and Tnf, before and after treatment and found that their expression was notably downregulated." (PMID 39769019, 2024). "Moreover, both periodontitis and OA are mediated by proinflammatory cytokines such as interleukin (IL)-1β and tumor necrosis factor (TNF)-α64." (PMID 38383594, 2024). "Additionally, the periodontitis-affected gingiva also produced more IL-1β and less Opg than the controls, as evidenced by RT‒qPCR." (PMID 38670955, 2024). "While elevated salivary IL-6 levels may indicate local inflammation in periodontitis, elevated IL-1β levels suggest its participation in thyroid pathophysiology and as a potential marker for the disease." (PMID 39063437, 2024). "Meanwhile, in rats with glucocorticoid-induced osteoporosis submitted to periodontitis, ATV at 27 mg/kg decreased bone loss, reduced myeloperoxidase (MPO), TNF-α, IL-1β, IL-6, and IL-8, and increased IL-10, glutathione (GSH), superoxide dismutase (SOD), and catalase (CAT) levels." (PMID 39476053, 2024).
periodontitis (continued). "ET-1 plays an important role in the pathogenesis of periodontitis; previously reported found that exposure to Porphyromonas gingivalis induces ET-1 secretion from endothelial cells and stimulates inflammatory cytokines such as IL-1β and TNF-α." (PMID 38874661, 2024). "Polymerase chain reaction (PCR), used for the detection of periodontal pathogens in aggressive periodontitis, showed an increase of IL-1β, produced by macrophages and monocytes, in early stages of inflammation, which would signify the important role of local inflammation on systemic inflammation." (PMID 39679199, 2024). "A well-studied gram-negative subgingival organism thought to be involved in driving periodontitis, P. gingivalis, was shown to induce gene expression of IL-1β and IL-18 cytokines in gingival tissues and through NLRP3 inflammasome activation to induce alveolar bone loss in mice." (PMID 38817019, 2024). "Therefore, we evaluated the effect of HKT on pro-inflammatory mediators iNOS and COX-2 and the major inflammatory cytokines of periodontitis, IL-6, IL-1β, and TNF-α, in an actual inflammatory situation." (PMID 38790655, 2024). "Our findings that periodontitis and MetS cause a significant increase in thr serum TNF-α level and IL-1β/IL-10 ratio and that the combined presence of these diseases exacerbates systemic inflammatory stress are compatible with the consensus in previous studies." (PMID 39590401, 2024). "IL-1β, which triggers a series of inflammatory reactions and bone resorption, has become a therapeutic target for autoimmune and autoinflammatory diseases such as rheumatoid arthritis, gout and type II diabetes mellitus in addition to periodontitis." (PMID 39012553, 2024). "Patients with hypothyroidism, especially those who had periodontitis, also showed a significant increase in salivary IL-1β levels, which may indicate a biomarker for the disease." (PMID 39063437, 2024). "Moreover, it has been shown that, IL-1β is considered a remarkable inflammatory biomarker in the development and progression of gingivitis and periodontitis." (PMID 38431633, 2024). "Additionally, inflammatory markers such as IL-1b, IL-6 and TNF-α are associated with periodontitis and HIV, and possibly elicit HIV reactivation." (PMID 38885222, 2024). "Similarly, the hepatic expression of proinflammatory cytokines IL-6 and IL-1b observed in MetS and periodontitis are further enhanced when both processes occur simultaneously." (PMID 37176029, 2023). "The conversion of pro‐IL‐1β and pro‐IL‐18 into the activated form IL‐1β and IL‐18 is mediated by a multiprotein complex termed the inflammasome, which regulates several diseases including periodontitis." (PMID 37506160, 2023). "As such, higher levels of IL-1β and RANK-L may contribute in sequence to an advanced stage and progression of periodontitis, in addition to being associated with PPD and CAL increases." (PMID 36769650, 2023). "The NLRP3 inflammasome, which is responsible for IL-1β secretion, significantly contributes to alveolar bone resorption by promoting osteoclast differentiation, and NLRP3 knockout reduced pathological alveolar bone loss in experimental periodontitis." (PMID 36782172, 2023). "Numerous cross-sectional studies have consistently demonstrated that individuals with periodontitis display higher serum IL-1β expression levels compared to healthy individuals, and these levels positively correlate with the clinical parameters of periodontitis." (PMID 38239915, 2023). "In addition, Synoviolin conditional KO mice with periodontitis had remarkably higher levels of IL‐1β and IL‐18 than WT mice with periodontitis in gingival tissues." (PMID 37506160, 2023). "Expression levels of IL1β, IL6, IL17α, and TNF-sf11 were significantly lower in P2×r5−/− mice compared to WT mice, and this reduction led to decreased periodontitis (gum disease) and decreased alveolar bone loss compared with WT mice, when challenged by LPS from Porphyromonas gingivalis." (PMID 36279087, 2023).